EPHA2 (EPH receptor A2)
Diseases named in the same sentence as EPHA2 in open-access papers (continued):
Sharing a sentence is not in itself a finding about the gene and the disease.
sarcoma (13 papers, 2012 to 2025). A usually aggressive malignant neoplasm of the soft tissue or bone. "While EphA2 has been identified as receptor for hepatitis C virus and Kaposi’s sarcoma-associated herpes virus binding and entry, this is the first time EphA2 has been shown to function as a receptor for a bacterial pathogen." (PMID 25906164, 2015). "In paediatric sarcomas, EphA2 acts as a critical oncoprotein that regulates tumour angiogenesis and aggressiveness, with EphA2 shown to be the most abundant upregulated cell surface receptor on OS cells." (PMID 39763064, 2025). "The study provides a foundational basis for the clinical evaluation of EphA2‐targeted CAR‐NK cell therapy across a spectrum of paediatric sarcomas." (PMID 39763064, 2025). "This study developed and validated a novel CAR‐NK cell therapy targeting the ephrin type‐A receptor‐2 (EphA2) antigen, which is highly expressed in various paediatric sarcomas." (PMID 39763064, 2025). "We validated EphA2 expression in sarcoma cell lines available in our laboratory and tested EphA2‐CAR‐NK cells against these cell lines using a Calcein AM cytotoxicity assay." (PMID 39763064, 2025). "In summary, these results indicate the potential of developing an EphA2‐CAR mRNA sequence based on the 4H5 clone for therapeutic use against sarcoma." (PMID 39763064, 2025). "EphA2, while significantly overexpressed in sarcomas, is also present in some healthy tissues, including highly proliferating normal epithelial cells, posing a theoretical risk of unintended targeting." (PMID 39763064, 2025). "In sarcomas, various antigens are present, with ephrin type‐A receptor‐2 (EphA2) being one of particular interest." (PMID 39763064, 2025). "EphA2, a receptor overexpressed in multiple paediatric sarcomas, is identified as a viable target for CAR‐based immunotherapy due to its critical role in tumour progression and angiogenesis." (PMID 39763064, 2025). "EPHA2 knockdown has been shown to drive the inhibition of cell viability and migration in other types of sarcoma." (PMID 38612645, 2024). "When an antibody to EphA2 and an inhibitor to HSP90 are combined in a sarcoma murine model, mice are rendered free of sarcoma and this has been associated with reduced numbers of MDSC." (PMID 24829747, 2013). "Finally, we evaluated the anti‐tumour efficacy of EphA2‐CAR‐NK cells in distinct in vivo sarcoma models." (PMID 39763064, 2025). "Several other targets of interest such as insulin-like growth factor receptor 1 (IGF-1R), receptor tyrosine kinase-like orphan receptor 1 (ROR1), and Ephrin type-A receptor 2 (EphA2) are overexpressed in various sarcomas and few CAR T-cell therapy clinical studies are currently ongoing." (PMID 40940995, 2025). "Among Eph receptors, the role of EphA2 in different types of solid tumors, including carcinomas and sarcomas, is well established but it is often controversial, as EphA2 action can be pro- or antitumorigenic depending on ligand availability and/or cell/cancer model context." (PMID 39596256, 2024). "Although optimization will be required, these exciting developments pave the road towards further testing of EPHA2 CAR T cell-directed therapies in childhood sarcoma patients, ideally in combination with strategies that tackle the immunosuppressive barriers in these tumors." (PMID 34572932, 2021). "However, Eph and IGF1 signaling pathways cross-talk to regulate bone and skeletal muscle cells function and EphA2 and EphB4 exert oncogenic effects in different types of sarcomas, supporting the rationale for targeting Eph-dependent pathways in those tumors." (PMID 34440844, 2021). "A different study used the ephrin type-A receptor-2 (EphA2) as a target antigen, showing that EphA2-CAR-NK-92 cells suppressed local tumor progression and metastatic burden in lungs in a sarcoma orthotopic mouse model." (PMID 40519903, 2025).
sarcoma (continued). "We have validated the efficacy of delivering and generating EphA2‐CAR mRNA with m1ψ modification to NK92 and primary human NK cells, demonstrating enhanced target specificity against the EphA2 antigen in sarcoma cells." (PMID 39763064, 2025). "This exhaustion could potentially be reversed by equipping tumour‐infiltrating NK cells with enhancement‐of‐function genes such as a EphA2‐CAR and underscore the potential for developing a novel immunotherapeutic strategy for paediatric sarcomas." (PMID 39763064, 2025). "While tyrosine kinase inhibitors blocking EphA2 or VEGF-C signaling are already being tested as potential targets for sarcomas, no information about the biological role of ErbB3 in pediatric rhabdomyosarcoma is currently available." (PMID 23227212, 2012). "Here, we have selected EphA2 as a target for proof‐of‐concept purposes; however, identifying more selective markers that are minimally expressed in normal paediatric tissues remains an active area of investigation to enhance the safety of CAR‐NK cell therapies for sarcoma." (PMID 39763064, 2025).
cortical cataract (12 papers, 2008 to 2023). A cataract (disease) that involves the lens cortex. "Our results in the Indian population agree with previous studies of the association of EPHA2 variants with cortical cataracts." (PMID 22412971, 2012). "In conclusion, our study identified the association of rs477558 and rs7548209 in EPHA2 with age-related cortical cataract in a Han Chinese population." (PMID 21686326, 2011). "Mutations in the Eph receptor A2 (EPHA2) lead to cortical cataracts in humans and in mouse models." (PMID 37571310, 2023). "The aim of this study was to examine whether EPHA2 polymorphisms were associated with the susceptibility to age-related cortical cataract in a Han Chinese population." (PMID 21686326, 2011). "While genetic predisposition is known to be a major contributing factor to age-related cortical cataract, our study has identified and characterized genetic variants of the EPHA2 gene in human, and both common and rare variants confer risks for cortical cataract." (PMID 19649315, 2009). "Our data show an increase in oxidized glutathione (GSSG) in lenses of Epha2+/− mice at the age when they develop severe cortical cataracts, suggesting an increase in reactive oxygen and/or nitrogen species in these lenses." (PMID 34495288, 2021). "In summary, we have confirmed previously reported associations of two candidate SNPs (rs7543472 and rs1120867) within the EPHA2 gene with cortical cataracts in an Indian population." (PMID 22412971, 2012). "Besides cortical cataracts, EphA2(-/-) mice sometimes displayed mild nuclear opacities at P21." (PMID 22140528, 2011).
esophageal cancer (11 papers, 2019 to 2025). A primary or metastatic malignant neoplasm involving the esophagus. "To date, the exploration of CAR-T cells therapy in esophageal cancer has been limited, with only EphA2, HER2, MUC1, and CD276 being identified as potential therapeutic targets in preclinical studies." (PMID 40510363, 2025). "DS-8895a was safe and well tolerated up to 20 mg/kg in patients with advanced solid tumors (Step 1) and EPHA2-positive gastric or esophageal cancer (Step 2)." (PMID 31412935, 2019). "We aimed to assess the safety, tolerability, and pharmacokinetics (PK) of DS-8895a administered in repeat doses to patients with advanced solid tumors and EPHA2-positive gastric or esophageal cancer in this first-in-human study of DS-8895a." (PMID 31412935, 2019). "In Step 2, patients with EPHA2-positive gastric or esophageal cancer were enrolled." (PMID 31412935, 2019). "Ephrin type A receptor 2 (EphA2) and HER-2, highly expressed in ESCC, are common targets of CAR T-cell therapy and have been verified to effectively kill esophageal cancer cells." (PMID 35814365, 2022). "Additionally, in esophageal cancer, it activates the EGFR-EFNA1/EPHA2-VEGFA signaling pathway, enhancing tumor cell proliferation, migration, and invasion." (PMID 39995671, 2025).
renal cell carcinoma (11 papers, 2014 to 2025). "EPHA2 is overexpressed in renal cell carcinoma, associated with more advanced disease and angiogenesis and has been implied as a mediator of sunitinib resistance in RCC." (PMID 37940875, 2023). "While in renal cell carcinoma, miR-141/200c suppresses cell proliferation and metastasis by targeting EphA2." (PMID 30041660, 2018). "GSEA analysis by using the ccRCC gene pool from TCGA database indicated that genes upregulated by high YB1 and EphA2 expression were enriched in the multiple-drug-resistance pathway, and genes upregulated by high EphA2 expression were enriched in renal cell-carcinoma pathway." (PMID 32814829, 2020).
Ewing sarcoma (10 papers, 2012 to 2025). A small round cell tumor that lacks morphologic, immunohistochemical, and electron microscopic evidence of neuroectodermal differentiation. "Likewise, EPHA2 induces genetic mutations in chondrosarcoma and amplifies tumor growth, migration and angiogenesis in Ewing’s sarcoma." (PMID 35563562, 2022). "Regarding our findings that the EphA2 receptor promotes migration and invasion of OS cells, a previous investigation of the role of EphA2 in Ewing sarcoma (ES) determined that high EphA2 expression is associated with the metastatic phenotype." (PMID 39056783, 2024). "Given the known roles of EPH/ephrins, particularly EPHA2, in promoting angiogenesis and tumorigenesis, their involvement in Ewing sarcoma pathogenesis, prognosis, and therapy is under exploration." (PMID 38612645, 2024). "The authors confirmed in silico that the expression of EPHA2 in samples retrieved from patients with Ewing’s sarcoma was higher compared to normal tissues." (PMID 35563562, 2022). "In ostesarcoma and Ewing sarcoma preclinical models, EphA2-directed chimeric antigen receptor (CAR) T-cell therapy showed potent in vitro and in vivo anti-tumor efficacy." (PMID 34440844, 2021). "For example, in Ewing sarcoma (ES) EphA2 promoted angiogenesis via ligand- (and caveolin-1)-dependent signaling, while en-hancing tumorigenicity, migration and invasion in vitro and in vivo, in an S897 depend-ent manner." (PMID 33572284, 2021). "Our immunohistochemical analysis demonstrated that EphA2 was also expressed at the protein level in ten out of ten samples representing clinical pediatric Ewing’s sarcoma." (PMID 23227212, 2012). "As a positive control for the Ewing’s samples, and again consistent with the in silico findings, all ten analyzed Ewing’s sarcoma samples demonstrated variable degrees of immunohistochemical EphA2 expression." (PMID 23227212, 2012). "Analysis of the Genesapiens database of human transcriptomes demonstrated statistically significant up-regulation of VEGFC and EPHA2 in Ewing’s sarcoma, and ERBB3 in alveolar rhabdomyosarcomas." (PMID 23227212, 2012). "In this study, we aim to broaden our validation of EphA2 as a therapeutic target across the bone sarcoma family, particularly in osteoblastic osteosarcoma, Ewing’s sarcoma and conventional chondrosarcoma, and at establishing bone sarcoma models, tailored according to patients’ tumor characteristics." (PMID 34831119, 2021). "Instead, EphA2 promoted Ewing sarcoma migration via ligand-independent phosphorylation at S897." (PMID 34440844, 2021). "Most Ewing sarcoma patients (90.4%) and cell lines express EphA2 protein." (PMID 34440844, 2021). "We also confirmed EphA2 expression in our Ewing’s sarcoma primary tumor samples and PDXs." (PMID 34831119, 2021). "EPHA2 (encoding EphA2, ephrin type A receptor 2), VEGFC (vascular endothelial growth factor-C), and FKBP1A (FK506 binding protein 1A) were overexpressed in Ewing’s sarcomas." (PMID 23227212, 2012). "While the overexpression of EphA2 in human Ewing sarcoma (ES) and OS tumor samples and cell lines has been reported previously, our study represents the first report of EphA2 expression in canine OS cells and tumors." (PMID 39056783, 2024). "Fisher’s exact test demonstrated that the relative overexpression EPHA2 and VEGFC in Ewing’s sarcoma was 15- and 17-fold, respectively, when compared to all pediatric cancer and normal samples (P<0.001 for both comparisons)." (PMID 23227212, 2012). "In summary, we found that EPHA2 and VEGFC are highly expressed in pediatric Ewing’s sarcomas and ERBB3 in pediatric rhabdomyosarcomas." (PMID 23227212, 2012). "Boxplot analyses providing comparisons within the different pediatric cancer samples indicated selective up-regulation of the mean expression of EPHA2 and VEGFC in Ewing’s sarcoma." (PMID 23227212, 2012).
Ewing sarcoma (continued). "Finally, the potent EPHA2 inhibitor ALW-II-41-27 demonstrated remarkable impeding effects on cell growth and cell viability when applied in osteoblastic osteosarcoma, Ewing’s sarcoma and conventional chondrosarcoma." (PMID 35563562, 2022). "In addition to EPHA2, we found that VEGFC expression was exceptionally high in pediatric Ewing’s sarcomas." (PMID 23227212, 2012). "Moreover, in Ewing sarcoma cells, a feedback loop exists between EphA2 phosphorylation and the MAPK pathway, as in fact silencing of EphA2 decreased both Akt and ERK phosphorylation while EphA2 phosphorylation at S897 was reduced exclusively by MEK inhibitors." (PMID 34440844, 2021).
esophageal squamous cell carcinoma (9 papers, 2020 to 2026). Esophageal squamous cell carcinoma (ESCC) is a type of esophageal carcinoma (EC) that can affect any part of the esophagus, but is usually located in the upper or middle third. "We found one experimental study that targeted EphA2 for esophageal squamous cell carcinoma (ESCC) CAR T-cell construction." (PMID 31936611, 2020). "Folic acid, a water-soluble B vitamin abundant in leafy green vegetables and animal liver, specifically inhibits the expression of the EphA2 gene and protein in esophageal squamous cell carcinoma (ESCC) ECA-109 cells, thereby suppressing the formation of VM structures." (PMID 41019994, 2025). "CAR-T cells that recognize EphA2 have shown the ability to recognize and assault esophageal squamous cell carcinoma (ESCC) in vitro." (PMID 40109582, 2025). "For example, whole-exome sequencing (WES) studies of paired esophageal squamous cell carcinoma (ESCC) tumors before and after radiotherapy revealed that the rate of EphA2 mutations was reduced after treatment, suggesting the need for functioning EphA2 for radio-resistance." (PMID 33572284, 2021). "In esophageal squamous cell carcinoma, miR-324-5p down-regulation is a prevalent change that stimulates cell division, migration, invasion, and tumor growth via triggering the EGFR-EFNA1/EPHA2-VEGFA signaling pathway by suppressing TNS4 expression." (PMID 36983713, 2023).
leukemia (9 papers, 2015 to 2024). A malignant (clonal) hematologic disorder, involving hematopoietic stem cells and characterized by the presence of primitive or atypical myeloid or lymphoid cells in the bone marrow and the blood. "Modifications of EphA2 expression may alter the susceptibility to Vδ1 γδ T-cell-mediated tumor recognition and killing that might be highly relevant in therapies targeting EphA2 in solid tumors and EphA2-positive leukemia." (PMID 34691070, 2021). "The EphA2 mAb IF7 coupled to Lutetium-177 showed therapeutic effect in an EphA2-expressing leukemia model with MLL translocation." (PMID 32397088, 2020). "In this report we explore the potential role of the EphA2 protein in the control of normal hematopoiesis and leukemia." (PMID 26083390, 2015). "Altogether, these results identify EphA2 as a potential radio-therapeutic target in leukemias with MLL translocation." (PMID 26083390, 2015). "Both the EphA2 mAb IF7 coupled to Lutetium-177 and then anti-EphA3 antibody IIIA4 linked to an α-particle-emitting Bismuth-213 payload showed therapeutic effect in EphA2 and EphA3 expressing leukemia models." (PMID 34926242, 2021). "To investigate if the antitumor activity of CD19-ENG T cells depended on significant T-cell expansion we injected BV173 leukemia-bearing mice on day 7 with 1 × 107 CD19-ENG or EphA2-ENG T cells that were genetically modified with a 2nd retroviral vector encoding eGFP.ffLuc." (PMID 27255991, 2016). "Thus, we investigated the possible functional effects of EphA2 expression on MLL-AF9 type leukemia along with the capacity of EphA2 mAb as a targeted antibody therapy or radio-immunotherapy." (PMID 26083390, 2015). "As is shown in supplementary S1 Fig in keeping with our analyses, EphA2 is variably but significantly over-expressed on leukemias with t(11q23) MLL rearrangement compared to normal hematopoietic stem cells, early progenitor cells (HPCs), CMPs, MEPs and GMPs (P <0.0001)." (PMID 26083390, 2015). "EphA2 monoclonal antibody therapy has been previously used in different types of cancers that express EphA2 in this report we explored the effect of targeting EphA2 using EphA2 monoclonal antibody and radiolabeled EphA2 monoclonal antibody in leukemias initiated by MLL translocations." (PMID 26083390, 2015). "In addition, the potential of EphA2 as a therapy target in MLL-AF9 leukemia was examined using the IF7 monoclonal antibody, which specifically binds to human and mouse EphA2 protein." (PMID 26083390, 2015). "This raises the possibility that targeting EphA2 might have therapeutic value in EphA2-positive leukemias." (PMID 26083390, 2015). "However, targeting MLL-AF9 leukemias with radiolabeled EphA2 monoclonal antibody significantly delayed the course of the leukemia in this mouse model." (PMID 26083390, 2015). "Indeed treatment with 177Lutetium-labeled anti-EphA2 mAb (IF7) significantly delayed the course of MLL-AF9 leukemia particularly when two doses of the drug were administered." (PMID 26083390, 2015). "Based on reports of over-expression of EphA2 in human leukemia and our own analysis of clinical samples, we examined expression of EphA2 gene in two models of leukemia, the MLL-AF9 model of acute myeloid leukemia and the BCR-ABL model of chronic myeloid leukemia." (PMID 26083390, 2015). "The available literature indicates expression of EphA2 transcript at significant levels in HSCs and various human malignancies however there is a limited knowledge on the specific role of this member of Eph family of RTKs in HSCs and leukemias." (PMID 26083390, 2015). "The elevated level of EphA2 expression in MLL-AF9 leukemias raised the possibility that this protein may have a role in MLL-AF9 leukemogenesis." (PMID 26083390, 2015).